STAT3 (signal transducer and activator of transcription 3)
Diseases named in the same sentence as STAT3 in open-access papers (continued):
Sharing a sentence is not in itself a finding about the gene and the disease.
hyper-IgE syndrome (89 papers, 2010 to 2026). A condition that is characterized by elevated serum IgE, dermatitis, and respiratory infections. "This pattern of elevated total IgE, but muted allergen-specific IgE mirrors observations in patients with an autosomal dominant form of an inborn error of immunity—hyperIgE syndrome (HIES) caused by STAT3 mutations." (PMID 40065718, 2025). "STAT3-hyper-IgE syndrome (STAT3-HIES) is an inborn error of immunity caused by heterozygous dominant-negative mutations in the signal transducer and activator of transcription 3 (STAT3)." (PMID 40878953, 2025). "Recessive LOF variants abolish JAK/STAT3 activation, manifesting as an autosomal-recessive Hyper-IgE syndrome with eczema, high IgE, eosinophilia, and recurrent bacterial infections." (PMID 40666020, 2025). "In the realm of immunity and inflammation, autosomal dominant STAT3 inactivating mutations associated with hyper immunoglobulin E syndrome highlight the causal role of STAT3 loss-of-function in human immune diseases." (PMID 40444012, 2025). "Mutations in the signal transducer and activator of transcription 3 (STAT3) gene are strongly associated with Hyper-IgE Syndrome (HIES), a rare immunodeficiency disorder characterized by elevated levels of IgE and recurrent infections." (PMID 41212476, 2025). "Certain conditions, such as defects in the IL-1R/TLR pathway (e.g., IRAK-4 deficiency), leukocyte adhesion deficiency, or hyper-IgE syndrome (STAT3 deficiency), can predispose individuals to severe and invasive Staphylococcal infections." (PMID 41431004, 2025). "Autosomal dominant STAT3 loss-of-function mutations, characteristic of STAT3 hyper-IgE syndrome (STAT3-HIES), and autosomal recessive DOCK8 deficiency are prototypical IEIs presenting with elevated eosinophil counts and elevated serum IgE levels." (PMID 40534692, 2025). "The first DCM patient with an identified mutation was a young girl with Coccidioides meningitis and hyper-IgE syndrome (HIES) caused by a dominant-negative mutation in STAT3." (PMID 38667927, 2024). "Recurrent infections are a hallmark of STAT3 dominant-negative hyper-IgE syndrome (STAT3 HIES), a rare immunodeficiency syndrome previously known as Jobs syndrome, along with elevated IgE levels and impaired neutrophil function." (PMID 39134362, 2024). "One piece of evidence of the tolerability of STAT3 inhibition came from the discovery that the inherited hyper-IgE syndrome (sometimes referred to as Job’s syndrome) is caused by one of several mutations in STAT3." (PMID 38611065, 2024). "Mutations in the signal transducers and activators of transcription 3 (STAT3) gene result in hyper-IgE syndrome(HIES), a rare immunodeficiency that causes abnormalities in immune system, bones and teeth." (PMID 37088831, 2023). "Such STAT3 LOF mutations are a major cause of hyper IgE syndrome (HIES), particular the AD form, characterized by cutaneous and respiratory infections, mucocutaneous candidiasis and eczema, as well as skeletal muscle and connective tissue disorders." (PMID 38255152, 2023). "A pathogenic STAT3 variant was detected from an adult female patient (Case 3) with a history of recurrent fever, pneumonia, and breast abscess who was diagnosed with hyperimmunoglobulin E syndrome in childhood." (PMID 37325673, 2023). "In particular, heterozygous autosomal dominant (AD) mutations in STAT3 have been associated with hyper-immunoglobulin E syndrome (HIES), a rare primary immune deficiency characterized by elevated serum IgE levels and recurrent skin and lung infections." (PMID 36292796, 2022). "Loss of Stat3 causes hyperimmunoglobulin E syndrome, presenting with skeletal disorders including osteoporosis, recurrent fractures, scoliosis, and craniosynostosis." (PMID 34496957, 2021). "Heterozygous Stat3 mutation in humans leads to Job syndrome (also named hyper-IgE syndrome), which is characterized by recurrent multiple organ infection along with skeletal, dental abnormalities." (PMID 34496957, 2021).
hyper-IgE syndrome (continued). "Hyper IgE syndrome (HIES) results from a dominant-negative STAT3 gene and is a primary immune deficiency characterized by atopic dermatitis (AD)-like dermatitis." (PMID 34867936, 2021). "Although homozygous recessive tyrosine kinase 2 (TYK) deficiency also can present with primary immunodeficiency with mild IgE elevation, STAT3 mutations are the predominant cause of sporadic and familial hyper-IgE syndrome." (PMID 33271763, 2020). "Signal transducer and activator of transcription 3 (Stat3), a conserved controller of cell proliferation, survival and regeneration, is associated with human scoliosis, cancer and Hyper IgE Syndrome." (PMID 28222105, 2017). "Further underscoring its role in human disease, dominant autosomal STAT3 mutations account for numerous symptoms in Hyper-IgE syndrome (HIES) patients such as misregulated TNFα levels and scoliosis." (PMID 28222105, 2017). "In humans, the suppression of Th17 production due to defective STAT3 gene mutation has been linked to hyper-immunoglobulin E syndrome (HIES)." (PMID 26340622, 2015). "DBD mutations in STAT3 (i.e., R382, F384, R423, V463 and V637) are a major cause of hyperimmunoglobulin E syndrome (HIES) and unexpected hyper-TNF-α promoter activity." (PMID 26384563, 2015). "One patient with high IgE serum concentration was confirmed to have a mutation in the STAT3 gene, leading to the diagnosis of Hyper-IgE syndrome." (PMID 25318568, 2014). "Based on the comprehensive medical history, auxiliary examinations, and the conclusive genetic finding of a de novo, likely pathogenic STAT3 variant, the final diagnosis was “Hyper-IgE Syndrome, cold abscess of the skin, anemia, and methicillin-sensitive Staphylococcus aureus infection”." (PMID 41458089, 2025). "Genetic factors in hyper-IgE syndrome, such as STAT3 mutations, may exacerbate this through impaired immune regulation, though facial deformities and sinusitis offer secondary pathways." (PMID 41155226, 2025). "Mutations in STAT3 result in hyper-IgE syndrome (HIES), a rare primary immunodeficiency." (PMID 37088831, 2023). "In the autosomal dominant (AD) forms of Hyper-IgE syndrome (HIES) due to loss-of-function STAT3 mutations (formerly known as Job syndrome), a rash may be observed in the newborn period, and may even be present at birth." (PMID 35601409, 2022). "In addition, patients with hyper-IgE syndrome (HIES) have a mutation in the transcription factor STAT3, which is important in several steps along the Th17 development pathway." (PMID 31963180, 2020). "In humans, STAT3 mutations cause a form of the Hyper IgE syndrome (AD-HIES; OMIM: 147060)." (PMID 31438472, 2019). "STAT3 mutations have been identified to cause the inflammatory disease Hyper IgE-syndrome (HIES)." (PMID 27089327, 2016). "The importance of the IL-17R pathway has been observed not only in knockout mouse models, but also in humans with rare genetic mutations that impact generation of Th17 cells or the IL-17 signaling pathway, including Hyper-IgE Syndrome (STAT3 or TYK2 mutations) or IL17RA or ACT1 gene deficiency." (PMID 25849644, 2015). "Its importance is evident in patients with hyper-IgE syndrome (HIES), resulting from mutations in STAT3." (PMID 41037009, 2025). "STAT3-hyper-IgE syndrome (HIES) has been primarily associated with GI manifestations, including gastroesophageal reflux disease, dysphagia, and abdominal pain." (PMID 36675441, 2023). "On the other hand, dominant-negative mutations of the STAT3 gene result in the classical autosomal dominant hyper-IgE syndrome (HIES), which is characterized by AD, recurrent infections, and elevated serum IgE levels and eosinophil counts." (PMID 38053996, 2023). "Hyper-IgE syndrome (HIES), a disease caused by STAT3 loss of function (LOF) and DOCK8 deficiency, is the classic example of an IEI that is frequently addressed to allergy units." (PMID 35757131, 2022).
hyper-IgE syndrome (continued). "Hyper-IgE syndromes (HIES) are a group of inborn errors of immunity (IEI) caused by monogenic defects such as in the gene STAT3 (STAT3-HIES)." (PMID 35655107, 2022). "The discovery of autosomal dominant STAT3 deficiency marked the first recognition of hyper-IgE syndrome (HIES) and the first primary immunodeficiency linked to elevated IgE." (PMID 34603803, 2021). "Dominant-negative, loss-of-function mutations in STAT3 in humans leads to autosomal dominant hyper-IgE syndrome (HIES) (AD-HIES), also known as Job syndrome." (PMID 31026808, 2018). "Hyper-IgE syndrome (HIES) caused by loss-of-function (LOF) mutations in STAT3 gene (STAT3 LOF HIES) is associated with dental and facial abnormalities in addition to immunological defects." (PMID 29868029, 2018). "We explored the significance of STAT3 NTD p.Trp37* variant in a patient with chronic pulmonary aspergillosis and a low Hyper-IgE syndrome (HIES) score." (PMID 39928202, 2025). "These symptoms are a hallmark of Hyper-IgE Syndromes (HIES), particularly those caused by STAT3 and DOCK8 deficiencies." (PMID 41035657, 2025). "The essential function of STAT3 in maintaining immune homeostasis was first shown in hyper-immunoglobulin E syndrome (HIES), a severe immunodeficiency due to dominant-negative mutations in the STAT3 gene." (PMID 37702894, 2023). "The patient iPSCs from STAT3-Hyperimmunoglobulin E syndrome (HIES), a primary immunodeficiency disease due to heterozygous STAT3 mutation, are base-edited using ABE to restore STAT3 signaling." (PMID 37340491, 2023). "STAT3 hyperimmunoglobulin E syndrome (STAT3-HIES) also referred to as autosomal dominant HIES (AD-HIES) is an inborn error of immunity characterized by the classic triad of eczema, frequent opportunistic infections, and elevated serum IgE levels." (PMID 37741967, 2023). "Hyper-IgE syndromes (HIES) are a group of inborn errors of immunity (IEI), of which the most frequent form is caused by monogenic defects in the gene STAT3 (STAT3-HIES)." (PMID 35655107, 2022). "Dominant-negative mutations associated with signal transducer and activator of transcription 3 (STAT3) signaling, which controls epithelial proliferation in various tissues, lead to atopic dermatitis in hyper IgE syndrome." (PMID 34867936, 2021). "STAT3 and TYK2 signaling alterations are associated with Hyper IgE syndrome (HIES), a rare immunodeficiency characterized by elevated serum immunoglobulin E (IgE), skin inflammation, and recurrent skin and lung infections." (PMID 34439323, 2021). "STAT3 hyper-IgE syndrome (STAT3-HIES) is a rare primary immunodeficiency that clinically overlaps with atopic dermatitis." (PMID 32912316, 2020). "As shown by studies in hyper-IgE syndrome (HIES) patients, the loss-of-function mutations of STAT3 abrogates the DC responsiveness to IL-10 and thereby impairs their tolerogenic functions and ability to stimulate differentiation of CD4+ T cells to regulatory T cells (Tregs)." (PMID 29921770, 2018). "Puncta formation was reversible, as determined by a decreased punctate signal after washout of oncostatin M. We analyzed STAT3 mutants, which have been reported in patients with hyper IgE syndrome and inflammatory hepatocellular adenoma (IHCA)." (PMID 29402895, 2018). "Furthermore, analyses of blood from patients with Hyper-IgE Syndrome (HIES), caused by dominant negative Stat3 mutations, showed normal Treg percentages but significant reduction of Treg expressed CCR6." (PMID 27974866, 2016). "Hyper-IgE syndrome (HIES) is characterized by elevated serum IgE levels, eczema, and recurrent skin and pulmonary infections, classically caused by autosomal dominant (AD) STAT3 loss-of-function variants." (PMID 41783139, 2026). "In addition to microthrombocytopenia, affected individuals often present with recurrent infections, eczema, eosinophilia and elevated IgE levels, suggesting a potential pathophysiological overlap with STAT3 hyper-IgE syndrome (HIES)." (PMID 41035657, 2025).
hyper-IgE syndrome (continued). "The observation that hyper-IgE syndrome caused by STAT3 loss-of-function mutations and EoE share some similar symptoms including atopic manifestations suggests that both diseases are triggered by an impaired balance between STAT1 and STAT3 activation." (PMID 40775363, 2025). "Decreased levels of RANTES and STAT3 could be a significant component in the disease pathogenesis of Hyper IgE Syndrome." (PMID 39229272, 2024). "The clinical relevance of the Th17-Th2 counter-regulatory mechanism is also highlighted by the monogenic Hyper-IgE syndrome, whereby defective STAT3 leads to the cardinal features of AD, including eczematous lesions on skin, S. aureus infections, and type 2 immune responses with high IgE." (PMID 36830738, 2023). "DOCK8 deficiency initially described as the AR form of hyper-IgE syndrome is now classified as a combined immunodeficiency, generally less profound than SCID, but still shares some clinical features with STAT3 deficiency adding to the complexity of the differential diagnosis of HIES with other IEI." (PMID 36703986, 2022). "Additionally, Tregs from patients with Hyper-IgE Syndrome (HIES), a primary immunodeficiency caused by dominant negative STAT3 mutations, showed significantly reduced surface expression of CCR6." (PMID 33315130, 2021). "For instance, inherited genetic mutations in the Th17 pathway (e.g., STAT1, STAT3, STAT4) are known to lead to several diseases such as chronic mucocutaneous candidiasis (CMC), Hyper-IgE syndrome (HIES) and autoimmune polyendocrinopathy–candidiasis–ectodermal dystrophy (APECED)." (PMID 31972980, 2020). "In addition, STAT3 mutations are associated with autosomal dominant-hyper-IgE syndromes (AD-HIES) and this association might allow differentiation of AD-HIES from disorders correlated with elevated serum IgE levels." (PMID 30134804, 2018). "The importance of this pathway in mediation of protective responses against bacterial infections is evident from the fact that patients with Hyper IgE Syndrome (HIES), caused by mutations in STAT3, are susceptible to recurrent staphylococcal infections and abscesses." (PMID 31557985, 2016). "A 43-year-old man with autosomal dominant (AD) signal transducer and activator of transcription 3 (STAT3) hyper-IgE syndrome (HIES) presented with a two-day history of fever (40 °C) and tremors." (PMID 41139156, 2025). "Hyper-IgE Syndrome (HIES) represents a heterogenous group of disorders majorly resulting from impaired STAT3 signaling." (PMID 33717144, 2021). "Next, the in vivo relevance of STAT3 in the regulation of the CAMP gene was investigated in immune cells from one patient with hyper-IgE syndrome (HIES)." (PMID 27633343, 2016). "This matches recent studies reporting a STAT3-dependence of T-cell development in patients with autosomal-dominant hyper-IgE syndrome (AD-HIES)." (PMID 22745821, 2012). "Atopy may present early in life in patients with STAT3 DN disease, which is also known as STAT3 hyper-IgE syndrome (STAT3-HIES)." (PMID 39859044, 2025). "Autosomal dominant disorders require one variant allele to cause disease, with a 50% chance of passing the variant and disease on to a child, for example STAT3 dominant-negative variants leading to hyper-IgE syndrome (AD-HIES)." (PMID 33864184, 2021). "Patients with Hyper-IgE Syndrome (HIES), also known as Job's syndrome, have impaired STAT3 signaling and diminished Th17 cell responses, and are vulnerable to CMC." (PMID 32185141, 2020). "Twelve patients with suspicion of Hyper-IgE syndrome were examined for molecular defects—4 were found to have pathogenic variants (1 in DOCK8, 3 in STAT3); 7 had no variants." (PMID 35729272, 2022). "Other known dominant-negative forms of STAT3 are the splice-variant STAT3β lacking the transactivation domain, and several STAT3 point mutants which are linked to the autosomal-dominant hyper-IgE syndrome (HIES)." (PMID 24192293, 2013).
hyper-IgE syndrome (continued). "To further corroborate an in vivo role for STAT3 in AMP-expression, we obtained cells from a patient with hyper-IgE syndrome (HIES)." (PMID 27633343, 2016). "Due to the identification of increased IgE levels (1060 IU/L) and National Institutes of Health (NIH) Hyper-IgE Syndromes (HIES) score of 30, STAT3 haploinsufficiency was suspected, but it was ruled out through direct genetic analysis." (PMID 39859960, 2024).